AQP4 (aquaporin 4)
Diseases named in the same sentence as AQP4 in open-access papers (continued):
Sharing a sentence is not in itself a finding about the gene and the disease.
tumor (continued). "Consequently, we performed qRT-PCR to investigate the expression of the two AQP4 isoforms in our patients’ tumor samples." (PMID 27483250, 2016). "Interestingly, AQP4 expression was found to be higher in the peritumoral area than in the tumor core, thus suggesting a correlation between the highest AQP4 expression and the highest ability to invade the surrounding tissue." (PMID 27367682, 2016). "It turned out that among patients in whom AQP4-IgG was detected incidentally in the course of a paraneoplastic evaluation, 93% had symptoms and signs of NMOsd and 27% had coexisting neoplasm, including breast, lung, thymic and uterine cervical cancer, B-cell lymphoma and monoclonal gammopathy." (PMID 26950113, 2016). "This is of interest because AQP4 was reported to be expressed in a variety of tumour tissues." (PMID 22260418, 2012). "Thus, data mining of AQP4-coexpressed genes indicated important physiological and anti-tumorigenic functions in both the normal and tumor cells." (PMID 21548930, 2011). "However, AQP4 deletion aggravates vasogenic (fluid leak) brain edema produced by tumor, cortical freeze, intraparenchymal fluid infusion, or brain abscess." (PMID 17347837, 2007). "The absence of anti-MOG and aquaporin-4 antibodies, normal oligoclonal bands, and unremarkable CSF studies created a diagnostic scenario that directed us towards inflammatory demyelination rather than neoplasia." (PMID 41280952, 2025). "Several in vitro and in vivo studies have reported reduced invasive capacity and migration in tumors after AQP4 depletion or downregulation by decreasing water permeability, which in turn upregulates transmembrane water fluxes during tumor or healthy astroglial cell movement." (PMID 38476871, 2024). "Also, AQP4 expression is related to tumor cell survival, migration, and invasion." (PMID 39043897, 2024). "In the high and low AQP4 expression groups, only the following five processes were significantly different between the high and low groups, including the release of cancer cell antigens, tumor antigen presentation, initiation and activation, eosinophil recruiting, and cancer cell clearance." (PMID 36523816, 2022). "Decreased expression of AQP4 in T regions could be related to the particular tumor microenvironment where low tumoral tissue oxygenation (hypoxia) promotes the spread of cancer cell spreading into healthy brain tissue in order to escape the hostile environment." (PMID 35187599, 2022). "AQP4 increases the expression and localization of (ClC2) and the potassium-chloride cotransporter 1 in invadopodia, resulting in water efflux and secondary cell shrinkage; this series of events may be vital for the movement of tumor cells through the ECM." (PMID 35847914, 2022). "Although the current study showed correlations for AQP expression with ADCuh, ADCst or ADCslow, we still cannot infer that the AQP1 or AQP4 distribution in the tumor center might be denser than peritumor as the immunohistochemical results were only obtained for the solid tumor part." (PMID 34712604, 2021). "Therefore, regular monitoring of serum AQP4 in AQP4‐positive paraneoplastic NMOSD patients may contribute to early detection of tumor recurrence or metastasis." (PMID 34520629, 2021). "Moreover, in the tumor area, AQP4 in the astrocytes around the vessels was decreased." (PMID 35083148, 2021). "Since AQP4 expression could not be detected in endothelial cells this channel does not seem to play a role in tumor-associated edema formation and resolution." (PMID 21548930, 2011). "Thus, also AQP4 expression was investigated in various tumor entities, a significant pro-tumorigenic effect of this channel could not be identified so far." (PMID 21548930, 2011). "Immunohistochemistry revealed high expression of AQP4 and glucose-regulated protein 78 (GRP78) in tumor cells." (PMID 41883892, 2026).
tumor (continued). "We evaluated the growth structures using multiplexed immunofluorescence staining, employing STEM121 to identify tumor cells, and specific markers such as CD31 for blood vessels, MBP for white matter, AQP4 for astrocytes, and NeuN for neurons." (PMID 40683881, 2025). "Among these, we found some key genes previously reported to be involved in tumor invasion and progression in other types of tumors, such as GPM6A, ABAT, GFAP, and AQP4." (PMID 40575267, 2025). "AQP4, for example, showed positive correlations with EMT and angiogenesis scores, consistent with its proposed role in tumour invasion and vascular permeability." (PMID 41007424, 2025). "Importantly, AQP4 has been implicated in several aspects of GBM progression, including enhanced cell migration, resistance to apoptosis, disruption of the blood–brain barrier (BBB), and the polarization of tumor-associated macrophages (TAMs) toward an immunosuppressive phenotype." (PMID 41324079, 2025). "In the context of NSCLC, the overexpression of AQP1, AQP3, AQP4, and AQP5 has been demonstrated to facilitate tumor angiogenesis, as well as the proliferation, migration, and invasiveness of tumor cells." (PMID 39440058, 2024). "Histological samples of tumor and normal brain tissues from the Human Protein Atlas database show the distribution of AQP1 and AQP4 proteins." (PMID 38476871, 2024). "Studies have demonstrated that a variety of cells, including CD20+ tumor cells, factor CD31+ endothelial cells, aquaporin-4 (AQP4)+ tumor cells, CD31+ endothelial cells, and CD20+ and AQP4+ tumor cells, engage in vessel formation." (PMID 37370872, 2023). "The population of tumor-derived astrocytes was identified by the upregulation of canonical astrocytic markers, including GFAP, AQP4, GJA1, and S100B." (PMID 35803925, 2022). "One of our patient's serum AQP4-IgG was transiently slightly elevated even though AQP4 was highly expressed in tumor cells, which indicates that AQP4 is not the main pathogenic antibody but might be induced by other underlying pathogenic antibody-antigen reactions." (PMID 36530632, 2022). "We found that AQP1 (5.83e−07), AQP2 (0.0146), AQP4 (0.000382), AQP6 (0.0221), AQP7 (0.00052), AQP9 (8.2e−07) had significant correlations with the pathological stages of the tumor." (PMID 35245343, 2022). "Since then, extensive research has been done regarding the role of AQP4 in GBM and its important function in tumor cell migration and proliferation is now well established." (PMID 32160197, 2020). "Since DW-MRI showed significant changes depending on the state of the tumor after IR, we also analyzed two major aquaporins (AQPs), AQP1 and AQP4, which are transmembrane water transporters that are primarily expressed in the brain tissue." (PMID 31803626, 2019). "In this context, the interactions of T and B cells are not random; they are a direct response to tumor-expressed antigens like AQP4." (PMID 40963604, 2025). "Multi-omics reveals the immense heterogeneity of the anti-AQP4 response, but the challenge is no longer just suppressing it; it’s understanding how to stop the tumor from continuously stimulating it." (PMID 40963604, 2025). "Notably, when PCA was repeated using only the six prognostic genes (AQP4, CDCA3, HJURP, KIF20A, PLK1, UHRF1), tumour and normal samples remained partially separable." (PMID 41007424, 2025). "Moreover, aquaporin 4 (AQP4) contributes to extended tumor cell migration, possibly passing through increasing water permeability and implication of AQP4 in tumor edema." (PMID 35326626, 2022). "With the increase of AQP4‐positive paraneoplastic NMOSD cases being reported, whether the occurrence of NMOSD is related to the origin of tumor, and whether cancer screening is needed when NMOSD is suspected have become the concern of clinicians." (PMID 34520629, 2021). "In the tumor area, irrespective of arteries or veins, AQP4 expression surrounding the vessels was weak." (PMID 35083148, 2021).
tumor (continued). "In some tumors, irrespective of the AQP4 immunoreactivity of tumor cells, endothelial cells displayed AQP4 cytoplasmic immunoreactivity." (PMID 33538957, 2021). "It is worth noticing that 74.4% (32/43) of serum AQP4‐positive patients did not perform tumor tissue AQP4 test, which should be improved in our future diagnosis process." (PMID 34520629, 2021). "The ADCuh at the center of the tumor showed a small positive correlation with AQP1, AQP4 and Ki67." (PMID 34712604, 2021). "Using high power resolution in the tumor area, we observed that GFAP expression was lower in the internal core of the tumor than in the peripheral area, CD34-positive vessels were surrounded by GFAP-positive astrocytes, and AQP4 was weakly expressed." (PMID 35083148, 2021). "In the non-irradiated group, AQP1 and AQP4 were expressed in GSCs at basal levels and no significant changes were observed in their expression during tumor progression." (PMID 31803626, 2019). "On the cellular level, aquaporin 4 was redistributed on the surface of the tumor cells, and in freeze fracture replicas no orthogonal arrays of particles were found." (PMID 26115524, 2015). "Although the small numbers prohibit reliable conclusions for the frequency of neoplasms in anti-AQP1-seropositive patients, they suggest that this frequency may be roughly similar with that of the anti-AQP4-seropositive patients." (PMID 24086369, 2013). "AQP9 expression within tumor parenchyma is not widespread, compared to abundant expression of the related water channel AQP4." (PMID 24086629, 2013). "Whilst aqp4 expression does not markedly increase from tumour progenitor to differentiated cell, its expression does increase markedly in rat differentiated cells." (PMID 22262958, 2012). "Specific TCR or BCR clonotypes that expand in response to tumor-expressed AQP4 could be developed into highly sensitive assays not just for monitoring NMOSD activity, but for detecting an occult cancer and monitoring its eradication following therapy." (PMID 40963604, 2025). "Unlike peritumoral edema, AQP4 expression is decreased in the blood-tumor barrier." (PMID 35910247, 2022). "Thus, although limited to the AQP4 pools detected with the BN-PAGE, we can conclude that the capacity of AQP4 to aggregate is not grossly impacted and is not related to tumor progression." (PMID 35187599, 2022). "Interestingly, irrespective of CAP treatment, tumor organoids were expressing 2-fold less Aqp1, Aqp4, and 10-fold less Aqp3 levels than normal organoids, whereas Aqp5 expression was increased." (PMID 35169122, 2022). "Since AQP4 water channels are part of the glymphatic system, we also postulate the possibility that PTBE in metastases may be related to glymphatic dysfunction with an increased periarterial influx of CSF into the tumor interstitium." (PMID 34722268, 2021). "Moreover, it has been suggested that AQP4-mediated water permeability at these sites, and tumor invasion, could be down-regulated by PKC activation, and AQP4 phosphorylation." (PMID 27367682, 2016). "Whether or not AQP4 exerts a tumor-suppressive or oncogenic effect warrants further investigation." (PMID 34113257, 2021). "Additionally, there is no widely accepted specific AQP4 inhibitor, and aquaporin inhibitors may be a novel class of anti-tumor agents." (PMID 34113257, 2021). "Under the serum‐free microfluidic tumor‐on‐chip model, GB3‐RFP cells expressed Nestin, the neural progenitor cell marker, but not GFAP, or AQP4, suggesting that GB3‐RFP cells retained their stem properties during invasion (Figure 3biii)." (PMID 35619544, 2022). "The ADCst, ADCslow and ADCuh at tumor center presented correlations with AQP1 and AQP4 while AQP9 did not correlate with any DWI metric." (PMID 34712604, 2021). "The ADCst at the center of the tumor showed a small negative correlation with AQP1, AQP4 and Ki67 (p < 0.05)." (PMID 34712604, 2021).
tumor (continued). "The ADCslow at the center of the tumor showed a small negative correlation with AQP1, AQP4 and a moderate negative correlation with Ki-67 (p < 0.05)." (PMID 34712604, 2021). "We conclude that there are two different influences on the expression and distribution of AQP4 and -1: firstly the influence of the ECM around the vessels within SEs showing no agrin and dystroglycan expression and therefore no OAPs in the tumor cell membranes." (PMID 26115524, 2015). "According to the GEPIA database, AQP1, AQP3, AQP4, and AQP9 were significantly expressed in LUAD tissues compared to normal lung tissues (p < 0.05), but some genes including AQP0, AQP5, AQP6, AQP7, AQP8, AQP10, and AQP11 were not differentially expressed between tumor and normal tissues." (PMID 34708074, 2021). "Moreover, three out of 22 patients were also diagnosed with a neoplasm (nephroma, non-Hodkin lymphoma or mammary cancer), which lead to the conclusion that AQP1-Ab might be considered a paraneoplastic factor like AQP4-IgG." (PMID 26950113, 2016).
neurological diseases (89 papers, 2010 to 2026). "Dysfunction of the glymphatic system, particularly involving AQP4, is associated with various neurological disorders characterized by pathological solute accumulation, such as Aβ and Tau clearance in AD." (PMID 39530196, 2025). "A significant number of neurological disorders are linked to changes in AQP4 expression or location." (PMID 36523816, 2022). "Previously, various animal models have provided evidence that loss or mislocalization of AQP4 affect neurological disease development." (PMID 36119130, 2022). "Aquaporin 4 (AQP4) is an important water channel in the central nervous system which is implicated in several neurological disorders." (PMID 34557603, 2021). "Aquaporin 4 has been implicated in neurological disorders including ischemia, stroke, and neuromyelitis optica." (PMID 34557603, 2021). "Because AQP4 is normally arranged in a polar manner, the increased mispolarization and expression of AQP4 cause neurological disorders." (PMID 32415357, 2020). "Nrf-2, acting as a transcriptional factor for cellular protective and antioxidative genes, plays a crucial role in the activation of AQP-4 expression in several neurological disorders especially brain injury in associated with oedema." (PMID 31080825, 2019). "Inhibiting AQP-4 expression decreases cerebral edema, thereby reducing the mortality and disability rates caused by nervous system diseases." (PMID 23935758, 2013). "The present results indicate that dysregulation of connexins in the context of neurological diseases might be associated with loss or mislocalization of AQP4 water channels." (PMID 32046059, 2020). "The growing body of literature suggests that the loss of AQP4 polarity—a loss in the organization of AQP4 channels to the perivascular membrane—is associated with increased vascular, inflammatory, and metabolic disturbances in the context of many neurological diseases." (PMID 41373689, 2025). "As a result, AQP4 may be a critical therapeutic target in the treatment of neurological disorders, and with the advancement of research, the study of AQP4 gene polymorphisms and a range of neurological diseases is also advancing." (PMID 36204139, 2022). "Viewing depolarized AQP4 as a malleable point provides new perspectives on neurological diseases as disorders of fluidic failure across systems." (PMID 41373689, 2025). "NMOSD has been established as a distinct neurological disorder upon the discovery of anti-AQP4 antibodies, and a new treatment era has finally dawned after the EMA approval of targeted therapies—satralizumab, inebilizumab, eculizumab and ravulizumab." (PMID 41464569, 2025). "Previous studies have demonstrated the dependency of parenchymal glymphatic clearance on AQP4 water channels in different neurological diseases." (PMID 38398003, 2024). "We recommend more studies for systematic screening of AQP4-Ab positivity in jSLE patients to confirm its relationship with neurological disorders." (PMID 37208665, 2023). "We significantly highlight the likely therapeutic approaches for glymphatic pathway in neurological diseases, and the importance of AQP4 and normal sleep architecture in this process." (PMID 37485040, 2023). "In this study, the total and differential WBC counts and their derivatives were compared between each of the groups with evaluated relapsing neurological diseases of the CNS (AQP4-IgG-positive NMOSD, MOGAD, and MS) and matched control groups." (PMID 37081126, 2023). "AQP4 and CXs have been investigated in neurological diseases such as Parkinson's disease, hypoxic brain edema, and traumatic brain injury." (PMID 35401278, 2022). "Currently the best clinical evidence for the use of complement inhibitors in neurologic disease comes from the use of C5 antibody eculizumab in AQP4+ NMOSD and MG." (PMID 36032156, 2022).